RNU1-82P (RNA, U1 small nuclear 82, pseudogene)
Gene: Small nuclear RNA gene on chromosome 7 (141,727,984 to 141,728,148, forward strand). Ensembl gene ENSG00000212153.
Homologues: Orthologues: chimpanzee U1 (97% identical), dog U1 (92% identical), rabbit U1 (92% identical), pig U1 (91% identical), rabbit U1 (91% identical), dog U1 (90% identical), pig U1 (88% identical), macaque U1 (87% identical), pig U1 (87% identical), pig U1 (81% identical), rabbit U1 (81% identical), guinea pig U1 (79% identical), and 6 more. Paralogues in human: RNU1-1 (92% identical), RNU1-2 (92% identical), RNU1-27P (92% identical), RNU1-28P (92% identical), RNU1-3 (92% identical), RNU1-4 (92% identical), RNVU1-18 (92% identical), RNVU1-29 (92% identical), U1 (92% identical), RNVU1-28 (91% identical), RNVU1-7 (91% identical), RNVU1-31 (90% identical), and 134 more.